ADA (adenosine deaminase)
Diseases named in the same sentence as ADA in open-access papers (continued):
Sharing a sentence is not in itself a finding about the gene and the disease.
tuberculosis (continued). "It is now well established that the observed increase in ADA, attributed to the rise in the levels of different types of ADA: increased ADA levels in tuberculosis, is primarily due to an increase in the activity of ADA isoenzyme (ADA-2), which is only found in monocytes-macrophages." (PMID 33740937, 2021). "The tuberculosis protein of MTB enters the pleural cavity and causes pleural inflammatory reaction, which leads to lymphocyte differentiation and proliferation, resulting in increased ADA content." (PMID 34425761, 2021). "For further validation of the diagnostic accuracy of ADA, IFN-γ, and IL-27 obtained from the Beijing cohort, we performed another prospective blinded study among the Wuhan cohort – a large urban city with high prevalence of tuberculosis." (PMID 32571326, 2020). "The proportion of patients with TPE who have low ADA activity may be higher than previously estimated, particularly in countries with a high tuberculosis burden." (PMID 31937286, 2020). "In high tuberculosis prevalence settings, in young patients, ADA, IFN-γ, and IL-27 could all accurately diagnosis TPE." (PMID 32571326, 2020). "ADA levels in non-tuberculous lymphocytic effusions rarely exceed the diagnostic cut-off for tuberculosis, and various ADA cut-off values have been used, ranging from 30 units/L to 50 units/L." (PMID 31534914, 2019). "ADA levels are particularly useful in areas where the prevalence of tuberculosis is high." (PMID 27287396, 2016). "Pleural effusion in our case was unlikely to be caused by tuberculosis, due to the normal ADA level and the negative mycobacterial culture findings." (PMID 27160723, 2016). "The ADA level in pleural effusion is well known to be elevated by tuberculosis." (PMID 26271927, 2015). "Among which, ADA, a purine-degrading enzyme that catalyze the conversion of adenosine and deoxyadenosine to inosine and deoxyinosine with the release of ammonia, is the most sensitive and specific marker for tuberculosis pleurisy diagnosis." (PMID 24984978, 2014). "In the Indian context where both scrub typhus and tuberculosis are endemic, ADA and scrub IgM may be helpful in identifying patients with scrub meningitis and in avoiding prolonged empirical antituberculous therapy in cases of lymphocytic meningitis." (PMID 23799119, 2013). "Estimation of Adenosine DeAminase (ADA) in ascetic fluid has value in diagnosing tuberculosis." (PMID 24167730, 2013). "For preoperative detection of tuberculosis, ascitic fluid adenosine deaminase (ADA) and PCR analyses have proven to be useful, however these tests may not be available in all settings." (PMID 23510576, 2013). "We note that the administration of empirical anti-tuberculosis treatment to patients with lymphocytic exudates and a high ADA level in pleural fluid when there is clinical suspicion of tuberculosis is a common practice in intermediate-to-high burden settings like our country." (PMID 22723878, 2012). "ADA was measured in 20 patients (17 patients of tuberculosis, 2 of malignancy and 1 of viral)." (PMID 21712918, 2011). "Thirteen patients had ADA level ≥ 70 U/L of which 11 had histopathologically proved tuberculosis and in the rest two patients, pleural biopsy tissue could not be obtained." (PMID 21139714, 2010). "Regarding pleural fluid ADA levels, commonly used as a diagnostic tool for tuberculosis when values exceed 35–40 U/L, our study revealed that the majority of cases in the children’s group surpassed this threshold, despite the absence of tuberculosis." (PMID 40361904, 2025). "However, many diseases other than tuberculosis, such as malignant pleural effusion, empyema and parapneumonic effusion (pleural infection), malignant lymphoma (ML), and autoimmune diseases, sometimes show high ADA levels." (PMID 36131272, 2022). "Additionally, we observed that IL-32 might regulate ADA expression in macrophages in the tuberculosis microenvironment." (PMID 35880892, 2022).
tuberculosis (continued). "Of the 52 subjects who had a high ADA level ≥ 39 UI suggestive of tuberculosis, only 13 of them (25%) received anti TB treatment." (PMID 32197582, 2020). "The utility of the adenosine deaminase (ADA) assay in the diagnosis of patients with pleural tuberculosis (TB) and human immunodeficiency virus (HIV) infection is controversial." (PMID 30428535, 2018). "Indeed, pleuritic fluid analysis revealed a transudate while cultures for acid fast bacilli and ADA test were negative; findings that were inconsistent with the possibility of tuberculosis as a cause of the clinical syndrome in our case." (PMID 21241493, 2011). "The prognostic value of plasma ADA was examined in patients diagnosed with and treated for PTB, excluding those with comorbid conditions known to elevate ADA levels independently of tuberculosis-related immune activation." (PMID 40572784, 2025). "ADA: adenosine deaminase; LDH: lactate dehydrogenase; TB: Tuberculosis; AFB: acid-fast bacilli; CBNAAT: cartridge-based nucleic acid amplification test." (PMID 41356863, 2025). "Clinical examination and specific pericardial fluid tests for adenosine deaminase (ADA) levels, gamma interferon (IFN-y), and polymerase chain reaction testing for Mycobacterium tuberculosis are all used to diagnose tuberculosis." (PMID 35894002, 2022). "Furthermore, IL-32 may modulate ADA expression in the tuberculosis microenvironment." (PMID 35880892, 2022). "A low level of ADA activity in TPE is occasionally observed, particularly in countries with high tuberculosis burden." (PMID 31937286, 2020). "In this study, patients in the low ADA group had a high proportion of ADA2 activity, similar to that of patients in the high ADA group, which implies a similar effect of tuberculosis-related immune reactions." (PMID 31937286, 2020). "China was one of the low-income countries, where sophisticated and expensive modern technologies (TB antibody test, adenosine deaminase, interferon-γ release test, and tuberculosis-infected T-cell detection, high-resolution computed tomography) developed slowly and continuously." (PMID 31077154, 2019). "Relationship of adenosine deaminase (ADA) levels with pulmonary tuberculosis (TB) and malignancy." (PMID 31016096, 2019). "IRISA-TB sensitivity, like that of ADA, was significantly higher than that of ULTRA, highlighting that tests requiring the express detection of M. tuberculosis will always struggle to reach the sensitivity of immunodiagnostic tests (which can greatly reduce the need for invasive biopsy procedures)." (PMID 31270183, 2019). "In contrast, higher lymphocyte counts, ADA activity, and IFN-γ concentration suggest a diagnosis of tuberculosis." (PMID 31455239, 2019). "In South Korea, an intermediate TB-burden country, clinicians prescribe anti-TB medication after identifying pleural fluid characteristics such as lymphocytic exudates with high ADA levels (>40 U/L) before microbiological confirmation of MTB, which is based on the Korea Guidelines for Tuberculosis." (PMID 28750069, 2017). "Our patient had emigrated from Mali three years prior to presentation, provoking high suspicion of tuberculosis; nevertheless, repeated AFBs from sputum and fluids, cultures, PPD, and ADA from pleural fluid and PCR from pericardial fluid came back negative." (PMID 27807484, 2016). "In TB endemic countries like India, patients with raised ADA levels could be a signal for tuberculosis where AFB positivity is low." (PMID 21629524, 2010). "Sarcoidosis must remain a differential diagnosis when ADA is markedly elevated, but direct microbiological evidence of tuberculosis is lacking." (PMID 41328078, 2025). "Tuberculosis was ruled out based on negative results for acid-fast bacilli smear and adenosine deaminase levels in pleural and ascitic fluids, as well as a negative whole-blood T-spot test." (PMID 39081322, 2024).
tuberculosis (continued). "Tuberculosis was confirmed bacteriologically (26 cases), clinically (four cases), pathology (two cases), and one case had an abnormal chest X-ray, abnormal Contrast-Enhanced CT chest, high ESR count, and high adenosine deaminase activity of pleural fluid." (PMID 36441785, 2022). "Other causes of pericardial effusion, such as malignancy, bacterial infection, and tuberculosis, were ruled out by cytology, bacterial culture, tuberculosis culture, and adenosine deaminase test." (PMID 36315499, 2022). "The combined value of the three tests for the diagnosis of tuberculous pleurisy was investigated to identify the correlation between pleural fluid interleukin-33 (IL-33), adenosine deaminase (ADA)and peripheral blood tuberculosis T cell spot detection (T-SPOT.TB)." (PMID 34425761, 2021). "Although elevated ADA levels usually indicate tuberculosis, the non-specific characteristics of cancer patients presenting with increased ADA levels and a positive tuberculin test can lead to misdiagnosis." (PMID 33996560, 2021). "He had no history or exposure of tuberculosis infection, no fever, no night sweats, negative tuberculosis test (PPD, T-spot), normal ADA in ascites, and no tuberculosis bacilli have been detected in ascites." (PMID 34915856, 2021). "ADA and tumor markers are not specific indexes in the differential diagnosis of tuberculosis and metastasis." (PMID 33996560, 2021). "Among the 17 subjects who were treated for tuberculosis, 4 of them (23.5%) had low ADA level suggesting they did not have peritoneal TB." (PMID 32197582, 2020). "His ADA test was at borderline, a chest X-ray was within normal limits, and a Mantoux test was negative which ruled out tuberculosis." (PMID 31472695, 2019). "A serum adenosine deaminase (ADA) test was also performed to rule out tuberculosis and was within normal limits." (PMID 31472695, 2019). "However, PF IgA MT10.3:MPT64 (86.2%) and it combined results with /−MPT64 or /−F2 identified all, except one, PLTB negative ADA, and, despite missing three or two of the positive ADA PLTB patients, the ELISA improved pleurisy tuberculosis detection (89.6%)." (PMID 31623558, 2019). "Adenosine deaminase assay (ADA) activity in pleural fluid can differentiate between pleural disease due to tuberculosis and effusion due to non-tuberculous lymphocytic effusion." (PMID 31534914, 2019). "Cultures remained negative; adenosine deaminase (ADA) from pleural fluid and PCR assay for tuberculosis from pericardial fluid came back normal as well." (PMID 27807484, 2016). "In those with suspected tuberculous pericardial effusion, adenosine deaminase (ADA), interferon-gamma, PCR analysis for tuberculosis, and pericardial lysozymes should be done in addition to the routine pericardial fluid acid-fast bacilli staining and mycobacterium culture." (PMID 27517082, 2016). "Bacterial staining tests for acid-alcohol fast bacteria and mycobacteria were negative, and serum adenosine deaminase (ADA) screening remained negative for tuberculosis." (PMID 24804262, 2014). "Furthermore, the erythrocyte sedimentation rate (ESR), adenosine deaminase (ADA) and C-reactive protein (CRP) levels, tuberculosis anti-body (TBAB) and γ-interferon antibody release test for Mycobacterium tuberculosis in the ascites were all normal." (PMID 24348779, 2014). "Our initial tentative diagnosis was tuberculosis, according to the high level of ADA and the negative Bence-Jones protein in urine and serum protein electrophoresis." (PMID 23514274, 2013). "In our case though PCR and acid fast staining were negative for tuberculosis, the persisting low haematocrit levels along with rising ADA levels led to the suspicion of tubercular ascites, and when treated with ATT, ascites was resolved completely." (PMID 24167730, 2013). "Paradoxically, retrospective study of 221 patients has illustrated that ADA levels >250 U/L do not generally occur in tuberculosis related effusions." (PMID 22448326, 2012).
tuberculosis (continued). "We have observed a highly statistically significant difference in the CSF - ADA levels of meningitis due to tuberculosis and non-tuberculous etiology (P < .01)." (PMID 21629544, 2010). "In conclusion, like ADA, IP-10 levels at the AUC-derived cut-point are not specific for tuberculosis, though at the lower cut-point they appear to be promising rule-out tests for TB in a high burden setting." (PMID 19277111, 2009). "Some biochemical indicators, such as tuberculosis interferon-gamma release assays (TB-IGRA), pleural effusion adenosine deaminase (pADA), pleural effusion lactate dehydrogenase (pLDH), the pLDH/pADA ratio, and pleural effusion cytological categorization, may serve as auxiliary diagnostic markers." (PMID 40757203, 2025). "Diagnostic thoracocentesis revealed straw-coloured exudative pleural fluid with elevated adenosine deaminase (ADA), confirming extrapulmonary tuberculosis (TB)." (PMID 41393185, 2025). "Adenosine deaminase (ADA) is an enzyme primarily produced by lymphocytes and macrophages in response to MTB antigens, having a crucial role in activating monocytes and facilitating their differentiation into macrophages, thus serving as a key marker of cellular immunity in tuberculosis." (PMID 40572784, 2025). "Additional markers, such as adenosine deaminase (ADA, suggestive of tuberculosis), amylase (for suspected esophageal rupture), N-terminal prohormone of brain natriuretic peptide (NT-pro-BNP, indicating heart failure), and triglycerides (greater than 110 mg/dL in chylothorax), may be helpful." (PMID 41230295, 2025). "Low; not suggestive of tuberculosis (TB meningitis often has higher ADA levels)." (PMID 39301403, 2024). "Similarly, CA 125 and adenosine deaminase activity are not specific in differentiating cancer of tuberculosis." (PMID 36674038, 2023). "Therefore, adenosine deaminase (ADA) and gene x-pert (tuberculosis nucleic acid testing) analysis of ascitic fluid is suggested in all patients with cirrhosis with difficulty uncontrolled ascites before labeling them as RA, especially in tuberculosis-endemic countries." (PMID 37396918, 2023). "This study also noted a negative correlation between age and ADA level in tuberculosis, which could affect the sensitivity of ADA-based criteria for tuberculous effusion." (PMID 37864205, 2023). "Adenosine deaminase (ADA), erythrocyte sedimentation rate (ESR), high-sensitivity C-reactive protein (hs-CRP), tuberculosis antibody (TB-Ab), and cancer antigen 125 (CA125) are commonly used for the diagnosis of TB." (PMID 32256565, 2020). "Higher lymphocyte counts, ADA activity, and IFN-γ concentration may suggest tuberculosis." (PMID 31455239, 2019). "Theoretically, tuberculosis antigen-specific responses like the one measured by IGRA should allow clinicians to distinguish PE from alternative diagnosis and provide greater discriminatory value than non-specific inflammatory biomarkers such as unstimulated IFN-γ or adenosine deaminase (ADA)." (PMID 26038718, 2015). "Therefore, experts have recommended measuring ADA levels in low-prevalence areas as a concentration <40 U/L almost exclusively rules out tuberculosis-driven effusions." (PMID 22448326, 2012). "None of the histopathologically proved tuberculosis cases had ADA level below 40 U/L." (PMID 21139714, 2010). "CSF adenosine deaminase levels were 4 U/L, which fall under the normal range and are not suggestive of tuberculosis (TB)." (PMID 41322879, 2025). "Finally, although the diagnosis of extrapulmonary TB is not the focus of this review, it is important to highlight the clinical relevance of the assessment of adenosine deaminase (ADA), which has been extensively used to diagnose these forms of tuberculosis." (PMID 39329871, 2024). "Laboratory analyses showed normal white blood cell counts, negative adenosine deaminase (ADA), and negative acid-fast bacillus smear, allowing for the exclusion of infection and tuberculosis." (PMID 39081322, 2024).
tuberculosis (continued). "Total adenosine deaminase (ADA, adenosine aminohydrolase, enzyme code: 3.5.4.4) in pleural fluid (P-ADA) is an accurate biomarker of tuberculosis independent of human immunodeficiency virus serology status." (PMID 33936323, 2021). "Theoretically, tuberculosis antigen-specific responses by IGRA should provide a discriminatory value superior to non-specific inflammatory biomarkers (e.g., unstimulated IFN-γ or ADA), but this is not the case." (PMID 33397312, 2021). "However, the diagnostic tests, including Xpert mycobacterium tuberculosis complex (MTBC)/resistance to rifampin (RIF), adenosine deaminase (ADA) activity, and the Quantiferon test, were all negative, and no clinical improvement was observed under anti-tuberculosis treatment." (PMID 40546536, 2025). "We report a rare case of TPE with only evidence of high ADA and negative AFB smear, TB polymerase chain reaction (PCR), and M. tuberculosis culture, highlighting the diagnostic complexity and the need for a high index of suspicion even when conventional tests are inconclusive." (PMID 41200634, 2025). "However, recent studies have shown that patients with empyema, malignancy, or rheumatoid pleurisy can also have high ADA levels, and negative results in older TPE patients and fluctuation were obviously affected by the patient profile and local tuberculosis (TB) prevalence." (PMID 33397312, 2021).